EIF3H (eukaryotic translation initiation factor 3 subunit H)
Diseases named in the same sentence as EIF3H in open-access papers (continued):
Sharing a sentence is not in itself a finding about the gene and the disease.
melanoma (1 paper, 2021). A malignant, usually aggressive tumor composed of atypical, neoplastic melanocytes. "Northern blot data indicated that TPPP3, DOCK2, and EIF3H were significantly upregulated in melanoma stem cells compared with cancer non-stem cells, while RNF128, DAPK1, and SYT7 were downregulated in melanoma stem cells." (PMID 33509274, 2021). "The in vivo data indicated that hnRNP A2B1 was required for tumorigenesis by affecting the splicing of TPPP3, DOCK2, EIF3H, RNF128, DAPK1, and SYT7, thus suppressing apoptosis of melanoma stem cells." (PMID 33509274, 2021). "On the other hand, the hnRNP A2B1 overexpression resulted in significant upregulations of TPPP3, EIF3H, and DOCK2 and downregulations of DAPK1, RNF128, and SYT7 in melanoma stem cells." (PMID 33509274, 2021). "Western blot data indicated that the hnRNP A2B1 silencing led to significant downregulations of TPPP3, EIF3H, and DOCK2 and upregulations of DAPK1, RNF128, and SYT7 in melanoma stem cells compared with the control." (PMID 33509274, 2021). "In this study, the results showed that hnRNP A2B1 suppressed apoptosis of melanoma stem cells through post-transcriptional regulation of apoptosis-related DAPK1, SYT7, RNF128, EIF3H, TPPP3, and DOCK2 genes." (PMID 33509274, 2021). "Taken together, these findings revealed that hnRNP A2B1 played a positive role in tumorigenesis of melanoma stem cells in vivo by affecting the splicing of TPPP3, DOCK2, EIF3H, RNF128, DAPK1, and SYT7, thus suppressing apoptosis of melanoma stem cells." (PMID 33509274, 2021). "Our findings revealed that the hnRNP A2B1-mediated splicing triggered the upregulation of TPPP3, DOCK2, and EIF3H, and the downregulation of RNF128, DAPK1, and SYT7 in melanoma stem cells, leading to the suppression of apoptosis of cancer stem cells." (PMID 33509274, 2021). "Collectively, it could be concluded that hnRNP A2B1 promoted tumorigenesis of melanoma stem cells via regulating the splicing of the precursor mRNAs of TPPP3, DOCK2, EIF3H, RNF128, DAPK1, and SYT7." (PMID 33509274, 2021).
metastatic tumors (1 paper, 2024). "Importantly, we found that human (colon to liver) metastatic tumors exhibited higher protein levels of EIF3H and HAX1 when compared with the paired primary tumor tissue and adjacent normal tissue from human patients with CRC." (PMID 38514606, 2024).
non-small cell lung carcinoma (1 paper, 2022). A group of at least three distinct histological types of lung cancer, including non-small cell squamous cell carcinoma, adenocarcinoma, and large cell carcinoma. "Researchers have found the amplification of eIF3H gene in colorectal cancer and non-small cell lung cancer (NSCLC) through genome-wide analyses and fluorescent in situ hybridization (FISH)." (PMID 35574327, 2022).
Obesity (1 paper, 2025). Accumulation of substantial excess body fat. "Our study identifies O‐GlcNAcylation at Thr83 as a key modification in obesity‐driven tumor progression, facilitating EIF3H recruitment, YAP stabilization, and tumor‐enhancing functions." (PMID 39868848, 2025). "Overall, these findings reveal a critical interplay between adipocyte‐mediated metabolic reprogramming and EIF3H‐mediated YAP proteolytic control, offering promising therapeutic strategies to mitigate the adverse effects of obesity on TNBC progression." (PMID 39868848, 2025). "This study reveals that obesity‐driven metabolic dysfunction enhances YAP O‐GlcNAcylation, facilitating its stabilization by preventing ubiquitylation and degradation via EIF3H, thereby driving TNBC progression and chemoresistance." (PMID 39868848, 2025). "It is found that Retatrutide, an anti‐obesity agent, inhibits HBP and YAP O‐GlcNAcylation leading to increased YAP degradation through the deprivation of EIF3H‐mediated deubiquitylation of YAP." (PMID 39868848, 2025). "While our study focused on EIF3H‐YAP interactions, future investigations should also explore whether EIF3H‐mediated OGT stabilization contributes to YAP regulation and obesity‐driven tumor progression." (PMID 39868848, 2025). "Our study highlights a critical intersection between the metabolic reprogramming by adipocytes and the proteolytic regulation of EIF3H‐YAP, offering insights into their combined impact on the progression and therapy resistance of TNBC in the context of obesity." (PMID 39868848, 2025). "Given this context, it is plausible that obesity‐induced metabolic reprogramming may alter YAP glycosylation patterns, which could, in turn, affect YAP ubiquitylation by modulating interactions with the deubiquitinase EIF3H." (PMID 39868848, 2025).
pancreatic cancer (1 paper, 2021). "In the oncomine database, expression of KIAA1429, LRPPRC, IGF2BP2, IGF2BP3, and EIF3H was higher in pancreatic cancer than normal tissues." (PMID 34332578, 2021). "An m6Ascore based on the expression of IGF2BP2, IGF2BP3, KIAA1429, METTL3, EIF3H and LRPPRC is proposed as an indicator of TME status and is instrumental in predicting the prognosis of pancreatic cancer patients." (PMID 34332578, 2021). "The Compared with adjacent non-tumorous tissues, we found a higher level of EIF3H, IGF2BP2, IGF2BP3, KIAA1429 in all six pancreatic tumor tissues, LRPPRC was overexpressed in five pancreatic tumor tissues, while the expression of METTL3 decreased in four pancreatic tumor tissues." (PMID 34332578, 2021).
small cell lung carcinoma (1 paper, 2012). Small cell lung cancer (SCLC) is a highly aggressive malignant neoplasm, accounting for 10-15% of lung cancer cases, characterized byrapid growth, and early metastasis. "In small cell lung cancer, the overexpression of EIF3H indicates a positive therapeutic response to Iressa therapy." (PMID 22734884, 2012).
steatosis (1 paper, 2022). Increased lipid within the cytoplasm of cells. "RBM15, YTHDC2, HNRNPC, HNRNPA2B1, and EIF3H were related to steatosis." (PMID 36120320, 2022).
cancer (29 papers, 2004 to 2026). A tumor composed of atypical neoplastic, often pleomorphic cells that invade other tissues. "Eukaryotic initiation translation factor 3 subunit h (EIF3H) plays critical roles in regulating translational initiation and predicts poor cancer prognosis, but the mechanism underlying EIF3H tumorigenesis remains to be further elucidated." (PMID 38514606, 2024). "Three subunits of the eukaryotic initiation factor 3 (eIF3) complex are correlated with cancer development—subunit eIF3d possesses cap-binding activity; eIF3G is associated with cancer progression; eIF3h interacts with METTL3." (PMID 33808751, 2021). "In patients with BCLC Stage A HCC, greater expression of EIF3H was associated with shorter OS and more cancer recurrence compared with patients with less expression of EIF3H." (PMID 27340783, 2016). "EIF3H is a cancer-related gene and suggested as a CRC potential diagnostic biomarker." (PMID 35439935, 2022). "Studies have demonstrated that EIF3H exhibits modified expression in certain cancer diseases, which correlates with oxidative phosphorylation." (PMID 39965013, 2025). "It does this by recruiting eukaryotic translation initiation factor 3 subunit H (eIF3h) to the translation initiation complex, thus promoting cancer cell growth, survival and invasion." (PMID 34692544, 2021). "Overexpression of EIF3H promotes cancer cell growth, results in a malignant phenotype, and serves as a prognostic marker of recurrence and metastasis." (PMID 32867821, 2020). "METTL3 can promote cancer cell growth, survival, and invasion by recruiting eIF3h to the translation initiation complex and directly promotes oncogene translation independently of its MTase activity." (PMID 31921660, 2019). "Upregulation of EIF3H is an independent predictor for greater rates of cancer recurrence and shorter overall survival in HCC patients." (PMID 27340783, 2016). "Using siRNA methods, we noted that depletion of EIF3H in HCC cancer cell lines altered cell malignant phenotypes and reduced in vivo HCC tumor growth." (PMID 27340783, 2016). "Previous research demonstrated that EIF3H is involved in multiple cancers." (PMID 32867821, 2020). "To find out whether EIF3H enhances cancer metastasis ability in vivo, we then performed lung metastatic model assay." (PMID 32867821, 2020). "Levels of nine eIF3 subunits involving eIF3A, eIF3B, eIF3C, eIF3D, eIF3E, eIF3H, eIF3I, eIF3J, and eIF3M were significantly increased in cancer tissues, whereas the eIF3L expression level in tumours was independently decreased than that of normal tissues (p < 0.05)." (PMID 31885740, 2019). "Thus, to address this gap in our understanding, we recognized the limitations of previous experiments used in studying EIF3 in cancer, then applied this to examine the evidence linking EIF3H subunit to HCC." (PMID 27340783, 2016). "By preventing ferroptosis, EIF3H may contribute to the survival of cancer cells." (PMID 38419066, 2024). "However, METTL3 can also modulate the cancer process by directly promoting the translation of oncogenes via interaction with the translation initiation machinery through recruitment of eukaryotic translation initiation factor 3 subunit h (eIF3h)." (PMID 31921660, 2019). "In addition, upregulated EIF3H protein expression was found in all tested HCC cancer cell lines." (PMID 27340783, 2016). "Among those subunits, the overexpression of eIF3H has been found to be increased in several types of cancer, where it has been speculated to regulate translation of mRNAs specifically involved in cell growth or apoptosis and consequently may favor oncogenic transformation." (PMID 25166596, 2014). "Our results reveal upstream regulation layers of HAX1 and illustrates how oncogenic signals from Wnt-EIF3H link to βTrCP-HAX1 axis for promoting ERK activation and tumorigenesis in cancer." (PMID 38514606, 2024). "Finally, EIF3H could promote cancer progression in HCC via OGT." (PMID 37559097, 2023).
cancer (continued). "With regard to cancer, an m6A score based on the expression of IGF2BP2, IGF2BP3, KIAA1429, METTL3, EIF3H, and LRPPRC was reported as an indicator of pancreatic tumor microenvironment status and was a potential biomarker for patients’ prognosis." (PMID 37903783, 2023). "Proto-oncogenic EIF3H and EIF3I likely regulate the protein level of downstream factors to facilitate the developmental process of cancer." (PMID 35040374, 2022). "Taken together, these results suggested that hnRNP A2B1 regulated the pre-mRNA splicing of pro-apoptosis genes (DAPK1, SYT7, and RNF128) and anti-apoptosis genes (EIF3H, TPPP3, and DOCK2), thus leading to the suppression of apoptosis of cancer stem cells." (PMID 33509274, 2021). "In the NDRG1 module, PSMD2 is overexpressed in many cancer cells, whereas PABPC1, EIF4G1, EIF3H, EIF3E, and EIF3K are RNA translational control members." (PMID 26735889, 2016). "EIF3H/HAX1 axis promotes CRC tumorigenesis and metastasis in mouse orthotopic cancer model." (PMID 38514606, 2024). "As reported, TPPP3, DOCK2, and EIF3H act as oncogenes by suppressing apoptosis of cancer cells, while RNF128, DAPK1, and SYT7 function as tumor suppressors by promoting apoptosis of many types of cancer cells." (PMID 33509274, 2021). "Except EIF3E and EIF3F found down-regulated and conferred tumor suppressive activity in cancers, majority of EIF3 members including EIF3A, EIF3B, EIF3C, EIF3D, EIF3H, EIF3I and EIF3M were up-regulated and played important roles in tumor progression of multiple cancer types." (PMID 29568350, 2018). "Indeed, several translation initiation factors that are overexpressed in human cancer, including EIF4E, EIF4G, EIF3A, EIF3C, and EIF3H may also contribute to tumorigenesis." (PMID 28594900, 2017). "However, an EIF3 subunit promotes cancer are probably weak, as rigorous controls may be lacking or alternative interpretations are not ruled out, and how the EIF3H subunit stimulates protein synthesis and promotes malignant transformation of immortal cells is unclear." (PMID 27340783, 2016).
tumor (25 papers, 2004 to 2026). "Importantly, HAX1 overexpression increased tumorigenicity and demonstrated strong metastatic capability; therefore, it could reverse reduced tumor growth and restore compromised lung and liver metastasis caused by EIF3H KD." (PMID 38514606, 2024). "The eukaryotic translation initiation factor 3 subunit H (EIF3H) is postulated to be a critical factor in translational initiation, with emerging research indicating its potential involvement in promoting tumor invasion and metastasis." (PMID 41822359, 2026). "Further analysis through immunohistochemical staining of the tumor tissues indicated that EIF3H suppression reduced YAP accumulation." (PMID 39868848, 2025). "In obese nude mice, tumors derived from MDA‐MB‐231‐ CRISPR/Cas9‐mediated EIF3H knockout (EIF3H KO) cells also exhibited significantly slower growth and smaller tumor sizes compared to the control group." (PMID 39868848, 2025). "We showed that EIF3H KD led to reduced tumor growth and compromised orthotopic carcinogenic as liver and lung metastatic abilities were greatly decreased when compared with control." (PMID 38514606, 2024). "Further analyses showed that elevated EIF3H mRNA level was correlated with metastasis to lymph nodes and advanced AJCC stage, implying EIF3H role in tumor progression." (PMID 38514606, 2024). "EIF3H can enhance protein synthesis and promote tumor progression, especially promote the translation of certain oncogenes." (PMID 38514606, 2024). "Immunohistochemistry (IHC) staining on orthotopic tumor showed that EIF3H KD led to reduced levels of EIF3H, HAX1 and pERK1/2, and repressed cell proliferation (Ki67 staining), while HAX1 overexpression reversed these impacts caused by EIF3H KD." (PMID 38514606, 2024). "Significantly, combined targeting Wnt and RAF1-ERK1/2 signaling synergistically inhibits tumor growth in EIF3H-high patient-derived xenografts." (PMID 38514606, 2024). "The results illustrated that EIF3H depletion by lentivirus-based shRNA suppressed the HCC tumor growth markedly." (PMID 37559097, 2023). "Mechanistically, exosomal circLPAR1 was internalized by CRC cells, and it suppressed tumor growth, likely because exosomal circLPAR1 directly bound with eIF3h specifically suppressed the METTL3-eIF3h interaction, decreasing the translation of oncogene BRD4." (PMID 35164758, 2022). "METTL3 can interact with the transcription factor eIF3h to promote the translation of oncogenes and ultimately to catalyze and accelerate tumor growth and metastasis." (PMID 33643384, 2021). "Our study reveals an essential EIF3H-Snail signaling axis in tumor aggressiveness in ESCC and provides EIF3H as a promising biomarker for ESCC treatment." (PMID 32867821, 2020). "In this study, we verified that EIF3H is involved in different processes of tumor tumorigenesis and progression." (PMID 32867821, 2020). "To elucidate functional significance of EIF3H in tumor progression, we used EIF3H overexpression or knockdown KYSE150 and KYSE510 cells to detect the impact of EIF3H on cell growth." (PMID 32867821, 2020). "In summary, we demonstrated that EIF3H is responsible for tumorigenesis, tumor growth and metastasis of ESCC through stabilizing Snail, thus promoting the EMT phenotype in ESCC cells." (PMID 32867821, 2020). "The percentage of Ki67 positive tumor cells in lung tissues of shControl group is also slightly higher than the EIF3H knockdown groups." (PMID 32867821, 2020). "Xenograft and tail-vein lung metastatic mouse models of KYSE150 cells with or without EIF3H knockdown were also used to confirm the function of EIF3H on tumor growth and metastasis in vivo." (PMID 32867821, 2020). "Overall, our study demonstrates the importance of EIF3H in regulating ESCC tumor aggressiveness, and provides a potential therapeutic targets of ESCC." (PMID 32867821, 2020). "Taken together, these results indicate that EIF3H knockdown inhibits cell mobility and tumor metastasis in ESCC." (PMID 32867821, 2020).
tumor (continued). "Conversely, genetic inhibition of EIF3H represses ESCC tumor growth and metastasis in vitro and in vivo." (PMID 32867821, 2020). "The expression of EIF3H is upregulated in HCC tissues compared with paired non-tumor tissues from the same donor, thus linking upregulation of EIF3H to pathological hepatic changes." (PMID 27340783, 2016). "With hierarchical clustering analysis for 60 pairs of HCC tumor and normal tissue samples, we evaluated the role of EIF3H in HCC progression." (PMID 27340783, 2016). "We measured EIF3H expression in tumor tissues from 215 HCC patients with qRT-PCR and median expression was the threshold." (PMID 27340783, 2016). "We confirmed this in another dataset of 215 paired HCC and normal tissue samples, and noted that EIF3H expression is upregulated in HCC tissue compared with the paired non-tumor tissues." (PMID 27340783, 2016). "A two tailed t-test confirmed inhibition of tumor growth after EIF3H knockdown that was significant compared with controls (p=0.005)." (PMID 27340783, 2016). "Previous studies have shown that RFFL and HDAC2 are known to also promote tumor formation by inhibiting the apoptosis process, whereas EIF3H is known to increase cell proliferation, growth and survival and inhibit the apoptosis process." (PMID 24377043, 2013). "Furthermore, MDA‐MB‐231 cells with EIF3H knockdown mirrored the tumor cell growth and colony formation inhibition effects seen in." (PMID 39868848, 2025). "The results showed that EIF3H was significantly upregulated in the tumor samples." (PMID 38514606, 2024). "In addition, the administration of the combination of LGK974 and trametinib in EIF3H-high group significantly decreased Ki67-positive tumor cells and protein levels of p-ERK and c-Myc, while the impact on EIF3H-low group was less effective." (PMID 38514606, 2024). "Importantly, combination of Wnt inhibitor and RAF1/MEK inhibitor can suppress the tumor growth of patient-derived xenografts (PDXs) that have EIF3H/HAX1 overexpression." (PMID 38514606, 2024). "In addition, we further utilized xenograft mice models to investigate the role of EIF3H in the regulation of tumor growth in vivo." (PMID 37559097, 2023). "We found overexpression of EIF3H promotes tumorigenesis, tumor growth and metastasis in ESCC." (PMID 32867821, 2020). "Moreover, in in vivo xenograft model, tumor growth and the percentage of Ki67 positivity were markedly reduced in mice injected with EIF3H knockdown KYSE150 cells compared with the controls." (PMID 32867821, 2020). "Box plots showed that EIF3H is significantly upregulated in tumor tissues." (PMID 32867821, 2020). "The results indicated that EIF3H is overexpressed in tumor cell lines." (PMID 32867821, 2020). "Additionally, an oncogenic role for EIF3H in tumor progression and metastasis in this research is convincingly demonstrated in vitro and in vivo, which is in alignment with previous studies." (PMID 32867821, 2020). "Besides, it also takes part in EMT process and the knockdown of EIF3H suppressed tumor metastasis in vivo." (PMID 32867821, 2020). "EIF3H overexpression increases tumor cell proliferation, growth, and survival." (PMID 27340783, 2016). "Therefore, aberrant overexpression of eIF3h may contribute to tumor development by upregulating the translation of important mRNAs associated with cell proliferation." (PMID 36830614, 2023). "Whether EIF3H expression levels rise continuously during tumor progression?" (PMID 32867821, 2020). "This modification shields YAP from proteasomal degradation by recruiting the deubiquitinase Eukaryotic Translation Initiation Factor 3 Subunit H (EIF3H), leading to YAP stabilization, tumor growth, and diminished chemotherapy effectiveness." (PMID 39868848, 2025). "In the orthotopic CRC model, EIF3H knockdown decreases orthotopic tumor growth, and attenuates liver and lung metastasis, while HAX1 can rescue these phenomena under EIF3H knockdown." (PMID 38514606, 2024).